PRL (prolactin)
Diseases named in the same sentence as PRL in open-access papers (continued):
Sharing a sentence is not in itself a finding about the gene and the disease.
acromegaly (continued). "The specific detection of PRL immunoreactivity is important however, while mammosomatotrophs and mixed adenomas are clearly different entities, they are functionally distinct as a group from pure somatotroph adenomas." (PMID 24039977, 2013). "Among them, three, four, and one patient had a single increase in growth hormone, prolactin, and both hormone and prolactin concentrations, respectively, and were diagnosed with growth hormone tumors, prolactinomas, and mixed adenomas, showing acromegaly and/or prolactinoma symptoms." (PMID 39279998, 2024). "The current study shows that GH, IGF-1 and PRL concentration, tumor size and invasiveness, as well as granulation pattern may predict surgical outcome in acromegaly, whereas male sex, GH concentration and granulation pattern may also forecast the response to first-generation SRLs." (PMID 36187106, 2022). "In addition, compared with clinically functioning somatotroph adenomas, silent somatotroph adenomas were more common in women, presented with a lower percentage of GH immunoreactive cells, and were more frequently plurihormonal (GH/PRL or GH/PRL/TSH)." (PMID 30020466, 2019). "Median GH at acromegaly diagnosis was 9.3 ng/mL (IQR: 15.2), median IGF‐I × ULN at acromegaly diagnosis was 2.6 (IQR: 1.3) and median prolactin was 7.9 ng/mL (IQR: 7.7)." (PMID 40789673, 2025). "Regarding the PRL and HPG axes, our study demonstrates that total testosterone plays a pivotal role in regulating sex hormones in male patients with acromegaly." (PMID 39707075, 2025). "For patients with acromegaly, preoperative GH, FT3, TT, and PRL levels are correlated with POD1GH levels, with some variations observed between the sexes." (PMID 39707075, 2025). "Three common functional PAs, including prolactinoma secreting prolactin (PRL), acromegaly secreting growth hormone (GH), and Cushing disease secreting adrenocorticotropic hormone (ACTH), appear in approximately 75% of all PAs." (PMID 38311763, 2024). "Among the drugs used for acromegaly, dopamine agonists could exert a positive effect on ED, as demonstrated in a randomized clinical trial in which cabergoline treatment was shown to be effective in treating psychogenic ED in patients with normal or mildly increased PRL levels." (PMID 35364803, 2022). "Acromegaly in CNC: In up to 75% of patients with CNC, the asymptomatic elevation of GH, IGF-1 and/or prolactin or abnormal response to the thyrotropin-releasing hormone is observed." (PMID 33805450, 2021). "Biochemical documentation of acromegaly with varying combinations of basal and post-glucose GH as well as IGF-1 levels is provided in 10 of these 13 cases; PRL was measured in 7 and found to be elevated in three." (PMID 24119925, 2013). "Postoperatively, PRL levels decreased significantly in patients with acromegaly (p < 0.001), with no significant changes observed in FSH (p = 0.391; p = 0.412) levels, while LH levels increased significantly (p = 0.021; p = 0.051)." (PMID 39707075, 2025). "Furthermore, according to the 2022 WHO classification of PitNETs, acromegaly patients harboring PIT1 tumors were further categorized on the basis of the expression of GH and PRL by IHC." (PMID 40421250, 2025). "The clinical predictors of surgical failure and of fgSRL resistance in patients with GH&PRL-PAs are similar to those described in acromegaly without PRL, co-secretion." (PMID 40590355, 2025). "One patient, who was diagnosed with acromegaly with positive immunohistochemical staining for GH, ACTH, PRL, and LH, showed high ACTH (normal laboratory range: 3–66 pg/mL) and cortisol levels (normal laboratory range: 4.82–19.5 ug/dL), with a lack of suppression in dexamethasone tests." (PMID 38248047, 2024).
acromegaly (continued). "Later, a meta-analysis including 160 patients with acromegaly treated with cabergoline as monotherapy reported that 34% of them achieved normal IGF-1 levels (mean cabergoline dose was 2.6 mg/week), and hormonal remission was predicted by lower IGF-1 levels and high PRL levels at baseline." (PMID 40590355, 2025). "Thus, we concluded the clinical predictors of surgical failure and of fgSRL resistance in patients with GH&PRL-PAs are similar to those described in acromegaly without PRL co-secretion." (PMID 40590355, 2025). "According to the results of our study, the addition of cabergoline to SSA normalized IGF-1 levels in a considerable amount of acromegaly patients with a moderately elevated IGF-1 level, regardless of serum PRL levels." (PMID 35612842, 2022). "Possible coexistence of acromegaly due to pancreatic GHRH excess and prolactin-secreting or non-functioning pituitary tumour remains a diagnostic challenge in MEN1 patients." (PMID 33805450, 2021). "Acromegaly due to a pituitary GH-secreting tumor is not very frequent, but most patients with CNC present with a mild increase in GH, and sometimes in prolactin (PRL) secretion." (PMID 16756677, 2006).
amenorrhea (87 papers, 2006 to 2025). The absence of menses in a woman who has achieved reproductive age. "Other recent evidence suggests that having amenorrhea or using prolactin elevating antipsychotic drugs are associated with a higher risk for osteoporosis and fracture." (PMID 23968123, 2013). "This case may represent the first report of lithium causing amenorrhea through elevated prolactin levels." (PMID 38978861, 2024). "Together, elevated prolactin levels and amenorrhea are associated with the suppression of the gonadotropin-releasing hormone (GnRH), which leads to the reduced secretion of the luteinizing hormone (LH) and follicle-stimulating hormone (FSH) from the anterior pituitary gland." (PMID 38338751, 2024). "Additionally, primary hypothyroidism is often associated with increased prolactin level, which can cause puberty arrest and oligomenorrhea or secondary amenorrhea." (PMID 32733376, 2020). "In one case, prolonged escitalopram use caused amenorrhea with elevated ACTH and normal prolactin; menses resumed after switching therapy." (PMID 41426913, 2025). "Studies have shown that switching a patient (especially a woman with amenorrhea) from risperidone to a prolactin-sparing agent often restores normal menstrual function." (PMID 40589655, 2025). "The results demonstrated that CAB effectively reduced PRL levels, controlled androgen levels, and improved menstrual cycles in women with oligomenorrhea or amenorrhea." (PMID 40399716, 2025). "PRL levels are correlated with the duration of postpartum amenorrhea; in rats, these levels have been shown to decline postpartum after separation from the pup." (PMID 38997985, 2024). "It has been shown that excessive PRL secretion in females can lead to amenorrhea, as a result of the inhibition of gonadotropin-releasing hormone (GnRH) release by PRL." (PMID 39519010, 2024). "Most prolactin-secreting PitNETs occur in girls (5:1) and will present during or after puberty, with primary or secondary amenorrhea due to excessive prolactin secretion." (PMID 37416813, 2023). "Sustained high levels of PRL can lead to fertility problems, reduced libido, and amenorrhea because PRL affects reproductive organs." (PMID 36833950, 2023). "Breastfeeding confers natural protection to pregnancy for the first six months postpartum due to prolactin-induced anovulation and amenorrhea." (PMID 36337806, 2022). "After three months of treatment, 8 of 10 patients with amenorrhea had menses and serum prolactin levels decreased significantly at month 2-3 (p = 0.025)." (PMID 32117518, 2020). "We also have pilot data to suggest that up to 15 mg of aripiprazole can resolve elevated prolactin in women with amenorrhea." (PMID 23968123, 2013). "Postpartum amenorrhea during breastfeeding may be partly attributed to higher prolactin levels compared to women who ovulate during breastfeeding, as prolactin inhibits the pulsatile release of GnRH from the hypothalamus." (PMID 40004657, 2025). "The patient presented with a 2-year history of amenorrhea and elevated prolactin." (PMID 40949298, 2025). "Long-term use of opioids can increase the release of prolactin (PRL) and reduce the release of GnRH (gonadotropin-releasing hormone) with the development of gynecomastia, erectile dysfunction, and reduction in sexual desire in men and amenorrhea in women." (PMID 37111650, 2023). "Clinically and biochemically, they are similar to densely granulated somatotroph tumors, with florid features and elevated GH and IGF-1 levels, but they also have manifestations of prolactin excess, including amenorrhea and decreased libido, due to prolactin production by the tumor." (PMID 34067494, 2021). "Correcting prolactin levels improves symptoms like amenorrhea and other menstrual abnormalities." (PMID 24490071, 2013). "Scientists reported that amenorrhea develops at serum PRL levels above 60–100 ng/mL." (PMID 24490071, 2013).
amenorrhea (continued). "Menstrual disturbances like amenorrhea usually recover after prolactin levels have been normalized." (PMID 24490071, 2013). "The etiology of lactational amenorrhea may include the suckling stimulus, energy deficit related to the increased catabolic demands of lactation, increased sensitivity to estradiol feedback and elevated prolactin levels." (PMID 17650319, 2007). "Three months postoperation, the patient presented with amenorrhea and serum levels such that Luteinizing Hormone(LH) was suppressed (0.1 mIU/ml), FSH was normal and Testosterone(T) and PRL levels were elevated." (PMID 34248835, 2021). "Testing of the gonadal axis is indicated in the presence of hypogonadal symptoms or amenorrhea with measures of follicle stimulating hormone (FSH), luteinizing hormone (LH), prolactin, testosterone (in men), and estradiol in women." (PMID 25694832, 2015). "In women symptoms such as amenorrhea are investigated at an early time-point, and prolactin levels are usually not as high as in men." (PMID 40276548, 2025). "Hormones such as leptin, cortisol and prolactin do not seem to contribute the persistence of amenorrhea after weight normalization." (PMID 37773179, 2023). "Some projects, however, have reported that prolactin has a direct effect on bone and is not related to hypogonadal state and amenorrhea." (PMID 20163720, 2010). "In addition, checking for reproductive dysfunction (amenorrhea, follicle-stimulating hormone (FSH), luteinizing hormone (LH), estradiol) and measuring prolactin, thyroid-stimulating hormone (TSH), and human chorionic gonadotropin (hCG) is needed to rule out causes of amenorrhea other than AN." (PMID 28324124, 2017).
hypothyroidism (85 papers, 2009 to 2025). Abnormally low levels of thyroid hormone. "Impaired clearance of PRL from the circulation is another mechanism associated with HPRL in hypothyroidism." (PMID 39754184, 2025). "In contrast, subclinical or overt hypothyroidism is associated with exaggerated prolactin response to TRH which is reversed after achieving euthyroidism." (PMID 39037546, 2024). "Kp10 not only increased testosterone and LH levels but also blocked the increase in plasma PRL caused by hypothyroidism." (PMID 37798396, 2023). "The increased prolactin associated with hypothyroidism results in an increase in dopamine, the prolactin inhibiting factor, which also inhibits GnRH section both directly and through alterations in kisspeptin signaling." (PMID 37372963, 2023). "Hormonal panel was suggestive of anterior pituitary hormonal deficiency (secondary hypothyroidism, secondary hypocortisolism, low serum prolactin and low gonadotropins)." (PMID 36062035, 2022). "Serum hormonal workup was suggestive of anterior pituitary hormone deficiency (secondary hypothyroidism, secondary hypocortisolism, low serum prolactin and low gonadotropins)." (PMID 36062035, 2022). "Collectively, both an increased TRH level and decreased T3 level in the hypothyroidism are associated with elevated expression of the prolactin gene, promoting prolactin synthesis." (PMID 35269847, 2022). "The currently reported case had only moderately increased PRL levels associated with secondary hypothyroidism." (PMID 34342837, 2021). "Some disorders also cause elevated levels of prolactin, for example, hypothyroidism, renal failure and cirrhosis." (PMID 34737888, 2021). "Hypothyroidism is frequently associated with indirect increases in circulating PRL that in turn increase the risk of anovulation in women." (PMID 20149258, 2010). "The drug reduced prolactin levels and increased estradiol concentrations in women with overt disease, but both effects probably reflected causal relationships between more severe forms of hypothyroidism and prolactin excess and estradiol deficiency." (PMID 40647196, 2025). "Kp10 also blocks the increase in plasma PRL caused by hypothyroidism." (PMID 37798396, 2023). "For example, increased levels of TRH may raise prolactin levels, contributing to the amenorrhea associated with hypothyroidism." (PMID 28723963, 2017). "On the other hand, hypothyroidism reduces fertility, causing estrous cycle irregularities and spontaneous consecutive pseudopregnancies that are considered to be a consequence of the hyper secretion of prolactin (PRL) during proestrus (P) and estrus (E)." (PMID 20149258, 2010). "The majority—77% had had diabetes insipidus (DI) at time of presentation, 44% had hypothyroidism, 33% had growth hormone deficiency, 22% had adrenal insufficiency, 22% had gonadotropic deficiency, 22% had either delayed or precocious puberty, and one patient had elevated prolactin." (PMID 32943645, 2020). "The decrease in prolactin concentrations was statistically significant only in both subgroups of women with overt hypothyroidism." (PMID 40647196, 2025). "Concurrently, aberrant prolactin (PRL) secretion in patients with hypothyroidism suppresses gonadotropin axis function, contributing to ovulatory dysfunction." (PMID 41450879, 2025). "Two patients from the same study, diagnosed with mild hypothyroidism at an advanced age, showed a slightly low prolactin level and cystic pituitary mass." (PMID 38990976, 2024). "In the course of diagnostics, it is recommended to exclude renal failure, hypothyroidism or the usage of drugs affecting hypothalamic-pituitary regulation of PRL secretion." (PMID 38370355, 2024). "The patients reported herein had severe hypothyroidism, combined with increased PRL, decreased COR levels, and lower levels of LH, and normal GH levels." (PMID 39502127, 2024).
hypothyroidism (continued). "Hypothyroidism increased PRL levels fivefold (***P < 0.001) and reduced plasma LH (****P < 0.0001) and testosterone levels (**P < 0.01) compared to control." (PMID 37798396, 2023). "Our findings describe the inhibitory effects of hypothyroidism on the male gonadal axis and sperm quality and demonstrate that Kp10 treatment reverses high prolactin levels and improves gonadal function and sperm quality in hypothyroid rats." (PMID 37798396, 2023). "Of all the 179 patients in the PCOS cohort, 3.4% had unexplained HPRL despite complete investigation, including PRL chromatography, pituitary MRI, exclusion of hypothyroidism, pregnancy, and HPRL drugs." (PMID 38004264, 2023). "Some even proposed that the elevation of PRL levels in women with PCOS is a transient phenomenon and is likely related to underlying stress, use of offending drugs, or hypothyroidism." (PMID 36552931, 2022). "Hormonal tests revealed secondary hypothyroidism, secondary hypocortisolism and decreased serum prolactin." (PMID 36062035, 2022). "The first one implies TRH overstimulation of pituitary PRL secretion in hypothyroidism conditions; the second one relies on the reported ability of TH to enhance PRL-induced promotion of lobuloalveolar development in breast organ cultures." (PMID 35207645, 2022). "Chemically induced hypothyroidism increased plasma PRL concentrations similar to heat stress-exposed laying hens, and administration of T4 attenuated this effect with PRL concentrations near basal levels." (PMID 34827087, 2021). "According to another study, 5 of 8 patients had hypothyroidism, 1 had irregular menses, 7 had erectile dysfunction, and 4 had increased prolactin levels." (PMID 30902082, 2019). "Hypothyroidism can also induce elevation in vasoactive intestinal peptide, which is capable of increasing PRL secretion." (PMID 29403355, 2018). "PRL elevation was found in 21% of patients with overt hypothyroidism, and 8% of patients with subclinical hypothyroidism." (PMID 29403355, 2018). "The present data suggest that TCS-induced hypothyroidism presents the same scenario, as the elevated levels of serum PRL, TSH and TRH in 10-TCS mice were corrected by L-T4 administration." (PMID 29403355, 2018). "Overall, a higher proportions of patients that remained uncontrolled had prolactin elevation (4.2% vs. 0%), adrenal insufficiency (16.7% vs. 6%), and hypothyroidism (20.8% vs. 10.0%)." (PMID 28778166, 2017). "Abnormal findings on MRI or CT were observed in 40 (54.1%) patients; 10 (13.5%) patients had hypothyroidism, 9 (12.2%) patients gonadal insufficiency, 7 (9.5%) had adrenal insufficiency, and 1 (1.4%) had elevated prolactin." (PMID 28778166, 2017). "On presentation, 20 (16.5%) patients had gonadal insufficiency, 19 (15.7%) had hypothyroidism, 18 (14.9%) had adrenal insufficiency, and 1 (0.8%) had elevated prolactin." (PMID 28279153, 2017). "In a previous study, it was shown that FT4 administration in hypothyroidism normalizes PRL and LH levels, increased folliculogenesis and estradiol secretion, reverses menstrual abnormalities and increases spontaneous fertility." (PMID 28723963, 2017). "Low thyroid hormone levels, increasing thyrotropin-releasing hormone secretion, stimulates lactotrophs to produce prolactin, while hypothyroidism was found to induce sexual dysfunction." (PMID 26902871, 2016). "Hypothyroidism increased circulating prolactin and estradiol on estrus 5 to 7-fold and 1.2 to 1.4-fold respectively." (PMID 20149258, 2010). "Hypothyroidism results in increased levels of thyrotropin-releasing hormone, which increases prolactin secretion." (PMID 20046401, 2009). "In hypothyroidism, prolonged feedback mechanisms can cause an increase in thyrotropin-releasing hormone (TRH) from the hypothalamus, which stimulates the production of PRL." (PMID 40150506, 2025). "Moreover, hypothyroidism can affect the secretion of GnRH through increased prolactin levels, leading to hypogonadotropic hypogonadism." (PMID 40429435, 2025).